RNU6-57P (RNA, U6 small nuclear 57, pseudogene)
Synonyms: RNU6-57
Gene: Small nuclear RNA gene on chromosome 13 (41,354,557 to 41,354,659, reverse strand). Ensembl gene ENSG00000223280.
Homologues: Orthologues: chimpanzee U6 (96% identical), mouse Gm23096 (84% identical), guinea pig U6 (83% identical), dog U6 (82% identical). Paralogues in human: RNU6-1011P (88% identical), RNU6-609P (88% identical), RNU6-558P (87% identical), RNU6-949P (87% identical), RNU6-1060P (86% identical), RNU6-12P (86% identical), RNU6-13P (86% identical), RNU6-26P (86% identical), RNU6-31P (86% identical), RNU6-32P (86% identical), RNU6-33P (86% identical), RNU6-1 (85% identical), and 1289 more.